AQP4 (aquaporin 4)
Diseases named in the same sentence as AQP4 in open-access papers (continued):
Sharing a sentence is not in itself a finding about the gene and the disease.
delirium (3 papers, 2015 to 2025). A disorder characterized by confusion; inattentiveness; disorientation; illusions; hallucinations; agitation; and in some instances autonomic nervous system overactivity. "Dysfunction in certain components of the glymphatic system, such as AQP4 water channels, can directly affect oligodendrocytes, leading to the development and progression of WMLs, which in turn may produce direct delirium effects." (PMID 39857699, 2025). "In addition to epigenomic markers we drew attention to an astrocytic proteomic marker, the aquaporin-4 (AQP-4) protein which was found to be up-regulated in delirium." (PMID 26579527, 2015). "Astrocytic swelling due to aquaporin-4 (AQP-4) up-regulation was documented in SID and may explain why most known delirium biomarkers are released by astrocytes." (PMID 26579527, 2015).
dry eye (3 papers, 2011 to 2024). "On the other hand, significant alterations of AQP4 and 5 were reported in 2 rabbit models of dry eye (rabbits with experimental autoimmune dacryoadenitis and pregnant rabbits)." (PMID 38771571, 2024). "Whereas significant alterations in AQP4 mRNA levels have been observed in experimental dry eye and during pregnancy, the impact of AQP4 in LG ductal fluid production remains unclear." (PMID 38771571, 2024). "Our data also showed altered expressions of AQP4 and AQP5 during pregnancy and suggested that these changes may contribute to the altered LG secretion and dry eye symptoms during pregnancy." (PMID 22128232, 2011). "The fact that AQP4 and AQP5 expressions underwent significant changes during pregnancy suggests changes in their functional status which may potentially contribute to the changes of LG fluid secretion and dry eye symptoms during pregnancy." (PMID 22128232, 2011).
endothelial dysfunction (3 papers, 2021 to 2023). In vascular diseases, endothelial dysfunction is a systemic pathological state of the endothelium (the inner lining of blood vessels) and can be broadly defined as an imbalance between vasodilating and vasoconstricting substances produced by (or acting on) the endothelium. "Using this approach, we demonstrate the impact of peripheral infection on BBB water exchange, which appears to be mediated by endothelial dysfunction and associated with an increase in perivascular AQP4." (PMID 37013549, 2023). "We observed tight junction rearrangements, indicative of endothelial dysfunction, in five out of eight assessed leukodystrophies of different origin and an altered aquaporin-4 distribution in all." (PMID 34082828, 2021).
frontotemporal dementia (3 papers, 2018 to 2023). Frontotemporal dementia (FTD) comprises a group of neurodegenerative disorders, characterized by progressive changes in behavior, executive dysfunction and language impairment, as a result of degeneration of the medial prefrontal and frontoinsular cortices. "Further dysregulation of AQP4 may be occurring in neurodegeneration (AD and frontotemporal dementia (FTD)), given a higher presence of AQP4 in the cerebrospinal fluid (CSF)." (PMID 37085942, 2023).
hemorrhage (3 papers, 2020 to 2025). Loss of blood from the vascular compartment to the exterior or into nonvascular body space as a result of rupture or severance of the blood vessels. "AQP4 expression surrounding the capillaries was significantly increased 24 h after hemorrhage." (PMID 38892076, 2024). "Another study in 363 TBI patients likewise examined AQP4 tag-SNPs and found that certain AQP4 SNPs, including rs3763043 and rs3875089, were significantly associated with 6-month functional outcomes, though not with initial injury severity or hemorrhage." (PMID 40943104, 2025).
lymphoma (3 papers, 2017 to 2024). A malignant (clonal) proliferation of B- lymphocytes or T- lymphocytes which involves the lymph nodes, bone marrow and/or extranodal sites. "AQP4 expression was reduced in lymphoma areas with a decreased Ki-67 index where rare tumor cells were positive to AQP4, and endothelial cells displayed AQP4 expression on their abluminal side." (PMID 36077720, 2022).
meningoencephalitis (3 papers, 2019 to 2024). Inflammation of the meninges and brain, generally secondary to an infectious cause. "It showed a marked meningoencephalitis with astrocytic damage characterized by loss of GFAP and AQP4 within the lesions." (PMID 38310187, 2024). "This article reports meningoencephalitis-like manifestations, including fever, headache, neck resistance, seizures, and pleocytosis, accompanied by nausea and vomiting, in a patient with serum AQP4 antibody-positive area postrema syndrome (APS)." (PMID 36275714, 2022). "From the age of 7 years, an AQP4-IgG negative female patient had 10 disease recurrences, including 4 episodes of recurrent ON, 4 episodes of fever and meningoencephalitis, and 2 episodes of ON as well as meningoencephalitis." (PMID 31072329, 2019).
muscular dystrophies (3 papers, 2011 to 2023). "In conclusion, several studies have highlighted the reduction in AQP4 in muscular dystrophies despite having different causal genetic mutations." (PMID 36675000, 2023). "Aqp4, which is enriched in type II muscle fibers, has been shown to be associated with dystrophin and is lost or reduced in muscular dystrophy." (PMID 30089464, 2018). "Importantly, AQP4 expression is compromised in several muscle diseases, such as in hereditary muscular dystrophies, in which components of DGC are lost or strongly altered." (PMID 21552523, 2011). "Aquaporin-4 (AQP4) is a water channel expressed at the sarcolemma of fast-twitch skeletal muscle fibers, whose expression is altered in several forms of muscular dystrophies." (PMID 21552523, 2011). "This also indicates that the alteration of AQP4 expression observed in several forms of muscular dystrophy are probably not a consequence of a direct structural interaction of the water channel with DGC proteins." (PMID 21552523, 2011).
normal pressure hydrocephalus (3 papers, 2022 to 2026). A form of compensated hydrocephalus characterized clinically by a slowly progressive gait disorder (see gait disorders, neurologic), progressive intellectual decline, and urinary incontinence. "The essential role of AQP4 in the glymphatic system and in cerebral homeostasis in general is reinforced in this work and malfunction or alterations in the expression and function of brain AQP (AQP4/AQP1) has been associated with the development of chronic adult hydrocephalus or iNPH." (PMID 35454119, 2022).
peripheral nerve injury (3 papers, 2024 to 2025). Injury to a peripheral nerve. "In recent years, accumulating evidence has suggested the essential role of non-coding RNAs, including miRNAs, in the regulation of Cx43 and AQP4 in experimental models based on peripheral nerve injury." (PMID 39456773, 2024).
pseudotumor cerebri (3 papers, 2022 to 2023). Idiopathic intracranial hypertension is a neurological disorder characterized by isolated increased intracranial pressure manifesting with recurrent and persistent headaches, nausea, vomiting, progressive and transient obstruction of the visual field, papilledema. "From the study of AQP4 KO mice, two common brain pathologies, pseudotumor cerebri and cerebral edema, were hypothesized to involve AQP4 in their pathophysiology." (PMID 35847914, 2022).
renal failure (3 papers, 2011 to 2025). "Concurrently, uremic milieu in renal failure impairs AQP4 function, exacerbating toxic protein accumulation." (PMID 41174538, 2025). "Bumetanide, a diuretic used in renal failure and oedema, blocked NKCC1 and reduced AQP4 expression, correlating with a 33% reduction in oedema after 48 h, and when used in combination with TGN-020, caused attenuation of oedema by nearly 89% at 72 h after SCI." (PMID 34685662, 2021).
Seizure (3 papers, 2017 to 2023). A seizure is an intermittent abnormality of nervous system physiology characterized by a transient occurrence of signs and/or symptoms due to abnormal excessive or synchronous neuronal activity in the brain. "AQP4 down-regulation or miss-localization has been repeatedly linked to experimental epileptic seizures and observed in human tissue from epileptic patients." (PMID 29182533, 2017). "Many reports have focused on this topic and several factors have been explored such as inflammation, poor sleep quality, impaired aquaporin 4 water channel, glutamate overproduction and glutamate receptor overactivation after epileptic seizures." (PMID 38144207, 2023).
Senile plaques (3 papers, 2014 to 2023). Senile plaques are extracellular deposits of amyloid in the gray matter of the brain. "Moreover, the authors report that the increased expression of AQP4 in senile plaques occurred during early Aβ deposition, whereas AQP4 downregulation occurred in the later stage of Aβ plaque formation." (PMID 35153718, 2021).
spinal cord disease (3 papers, 2011 to 2025). "Since the EAE score is biased toward detecting spinal cord disease, the clinical phenotype may miss alternative lesion locations in AQP4-induced EAE." (PMID 39934927, 2025). "While all mice in a MOG35–55/CFA immunized control group developed severe EAE, none of the AQP4 immunization protocols resulted in the induction of a clinically manifest spinal cord disease or signs of visual impairment." (PMID 21264240, 2011). "However, active immunization with these AQP4 peptides did not induce signs of spinal cord disease." (PMID 21264240, 2011).
Vertigo (3 papers, 2018). An abnormal sensation of spinning while the body is actually stationary. "AQP4 dysfunction might be associated with migrainous episodes as well as vertigo accompanied by hearing loss and other auditory symptoms." (PMID 30250448, 2018).
angioedema (2 papers, 2015 to 2021). Swelling involving the deep dermis, subcutaneous, or submucosal tissues, representing localized edema. "Meanwhile, AQP4 acts a key role in angioedema and cytotoxic edema and is essential for the removal of angioedema." (PMID 34337080, 2021).
Arthritis (2 papers, 2021 to 2023). Inflammation of a joint. "Emerging evidence supports the notion that AQP4 overexpression in articular chondrocytes exacerbates the severity of adjuvant-induced arthritis in rats." (PMID 34362382, 2021). "It is worthy of note that overexpression of AQP4 in articular chondrocytes exacerbates the severity of adjuvant-induced arthritis in rats." (PMID 34362382, 2021).
aseptic meningitis (2 papers, 2024). Inflammation of the membranes surrounding the brain and spinal cord without a bacterial pathogen. "We describe the atypical clinical course and pathology results of a patient with anti-aquaporin-4 antibody (anti-AQP4-Ab)-associated NMOSD who developed aseptic meningitis followed by limbic-encephalitis-like presentation with extensive brain lesions upon treatment with rituximab and tocilizumab." (PMID 39077876, 2024). "aseptic meningitis and limbic encephalitis could represent a rare phenotype of anti-AQP4-Ab-associated NMOSD." (PMID 39077876, 2024).
astrocytic tumor (2 papers, 2007 to 2017). A glial tumor of the brain or spinal cord showing astrocytic differentiation. "One publication suggested that AQP4 could be used as a diagnostic marker to distinguish oligodendroglial and astrocytic tumors." (PMID 28423683, 2017).
atrial fibrillation (2 papers, 2022 to 2025). A disorder characterized by an electrocardiographic finding of a supraventricular arrhythmia characterized by the replacement of consistent P waves by rapid oscillations or fibrillatory waves that vary in size, shape and timing and are accompanied by an irregular ventricular response. "Myocardial interstitial edema is mainly caused by fluid leakage in heart failure and atrial fibrillation, and the low expression of AQP4 aggravates the accumulation of fluid between myocardial cells." (PMID 36295481, 2022). "Additionally, in our previous study, we confirmed that increased AQP4 is associated with fibrosis and calcium-handling proteins in an atrial fibrillation mouse model." (PMID 40650101, 2025). "As a potential therapeutic target, the role of AQP4 in the pathogenesis of heart failure and atrial fibrillation deserves further attention." (PMID 36295481, 2022). "Finally, five genes (FRZB, SFRP4, ETNPPL, AQP4, C1orf105) were found to be highly co-expressed in patients with heart failure and atrial fibrillation." (PMID 36295481, 2022). "However, in the present study, we analyzed the data at the gene transcription level and found that AQP4 showed low expression significantly in the datasets of heart failure and atrial fibrillation." (PMID 36295481, 2022).
B-cell non-Hodgkin lymphoma (2 papers, 2020 to 2025). The most common type of non-Hodgkin lymphoma. "So the current case is an unusual presentation of primary brain stem B cell non-Hodgkin’s lymphoma, which was initially misdiagnosed as NMO on the basis of clinical findings, slightly high AQP4 and magnetic resonance imaging that accorded with the characteristic imaging of NMO." (PMID 32161683, 2020).
cerebral astrocytoma (2 papers, 2019 to 2020). An astrocytoma that arises from the cerebral hemispheres. "Another group of scholars found a correlation between ADC_uh parameters and the AQP4 expression in the solid parts of the cerebral astrocytoma." (PMID 31595200, 2019).
cerebral malaria (2 papers, 2020 to 2021). A sequestration of Plasmodium falciparum in the brain, which can cause coma and/or seizures. "In comparison with the WT mice, AQP4-knockout mice showed earlier appearance and more severe signs of cerebral malaria with greater brain edema." (PMID 33796134, 2021). "This study showed that mice infected with P. berghei and showing cerebral malaria displayed a reduction of brain AQP4 at transcript and protein levels." (PMID 33796134, 2021). "However, AQP4 has been suggested to play protective roles in murine cerebral malaria." (PMID 33796134, 2021). "In addition, decreased AQP4 expression leads to increased brain water content in cerebral malaria." (PMID 32252790, 2020).
colorectal cancer (2 papers, 2020 to 2025). A primary or metastatic malignant neoplasm that affects the colon or rectum. "Within this final set, the largest proportion of studies addressed AQP1, followed by AQP5, AQP4, AQP3 and AQP9, for a diverse array of cancer types, including brain, lung, breast and colorectal cancers." (PMID 32679804, 2020).
Creutzfeldt-Jakob disease (2 papers, 2010 to 2012). "The increase in the expression levels of AQP4 has been reported in Creutzfeldt-Jakob disease, bovine spongiform encephalopathy and scrapie-infected transgenic mice." (PMID 22897917, 2012). "Enhanced expression of AQP4 in Creutzfeldt-Jakob disease (CJD) was first reported by Iwasaki’s laboratory." (PMID 21119882, 2010).
deafness (2 papers, 2023 to 2026). An inherited or acquired condition characterized by the complete loss of the ability to hear from one or both ears. "AQP4-deficient mice have hearing impairments of varying severity, up to the point of deafness, as revealed by the analysis of the auditory brainstem threshold." (PMID 41598359, 2026). "In the case of Aqp4, which is expressed in Hensen’s cells, Claudius cells, and inner sulcus cells as well as fibrocytes, loss of Aquaporin-4 water channels leads to profound deafness in mice by 4–5 weeks of age." (PMID 37854703, 2023).
Diarrhea (2 papers, 2017 to 2023). Abnormally increased frequency (usually defined as three or more) loose or watery bowel movements a day. "Diarrhea is commonly associated with abnormal water metabolism in the intestine, which is regulated by AQP3, AQP4, and AQP8 proteins." (PMID 37237988, 2023).
dysferlinopathies (2 papers, 2023). "In line with our results, one study had previously demonstrated a reduction between 23% to 95% in aquaporin 4 in six patients affected with dysferlinopathies." (PMID 37239109, 2023). "For example, dysferlinopathy patient biopsies revealed reduced AQP4 levels despite normal α1-syntrophin levels." (PMID 36675000, 2023). "In addition to DMD, patients with other NMDs, including Fukuyama-type congenital muscular dystrophy (FCMD), dysferlinopathy, and sarcoglycanopathy, also revealed reduced levels of AQP4, although its roles in pathogenesis and pathophysiology are unclear." (PMID 36675000, 2023). "While AQP4 reduction in FCMD correlates with reduced α-syntrophin in the muscle, immunostaining for α1-syntrophin is unchanged in dysferlinopathy patients, suggesting a distinct mechanism involved." (PMID 36675000, 2023).
dyslipidemia (2 papers, 2021 to 2025). "Further, dyslipidemia with low HDL is related to disease activity and disability in patients with AQP4 positive NMOSD." (PMID 34777231, 2021).
Heat Stroke (2 papers, 2017 to 2024). A condition caused by the failure of body to dissipate heat in an excessively hot environment or during PHYSICAL EXERTION in a hot environment. "Clinical case reports of sauna-associated death and fatal heat stroke have shown increased AQP3-ir in the skin epidermis and Aqp4 expression in the brain." (PMID 39335570, 2024). "Relative mRNA quantification using Taqman real-time PCR assay demonstrated increased calibrated normalized relative quantity (CNRQ) values of MMP9, CLDN5, OCLN, ZO1 and AQP4 in heat stroke cases." (PMID 28490769, 2017). "The present study, for the first time, reports increased cerebral MMP9, CLDN5, OCLN, ZO1 and AQP4 in heat stroke and suggest a crucial role of reference gene selection when using postmortem human tissues." (PMID 28490769, 2017). "In immunostaining, only AQP4 showed more intense staining in most heat stroke cases." (PMID 28490769, 2017). "Therefore, in heat stroke cases, AQP4 might play a beneficial role in eliminating accumulating water from the extracellular space of the CNS, suggesting an activation of the self-protective system." (PMID 28490769, 2017). "When those four validated reference genes, SDHA, POLR2A, IPO8 and HMBS, were used for normalization, increased cerebral expressions of AQP4, CLDN5, OCLN, ZO1 and MMP9 were detected in heat stroke group." (PMID 28490769, 2017).
Hyperkalemia (2 papers, 2022 to 2024). An abnormally increased potassium concentration in the blood. "While deletion of AQP4 caused a reduction of hyperkalemia-induced swelling in LRA, the swelling was higher in HRA, compared to Ctrl subpopulations." (PMID 38818517, 2024). "Surprisingly, we detected opposing effects of AQP4 deletion on volume changes in LRA and HRA during hyperkalemia, which was hidden during the initial analysis that included all cells together." (PMID 38818517, 2024). "The decreased volume of astrocytes from Aqp4–/– mice under exposure to OGD indicates an impairment of compensatory mechanisms that allow water influx into astrocytes, which we detected in the other models (hypoosmotic stress and hyperkalemia)." (PMID 38818517, 2024). "Overall, the lack of AQP4 channels had the opposite effects on volume changes in the LRA and HRA subpopulations, the lack of TRPV4 channels affected only the LRA, resulting in lesser volume changes in response to hyperkalemia." (PMID 38818517, 2024).
hypothyroidism (2 papers, 2023 to 2024). Abnormally low levels of thyroid hormone. "In addition, one AQP4-ON patient and one MOG-ON patient were positive for antinuclear antibodies (ANA), and one MOG-ON patient had hypothyroidism." (PMID 36969199, 2023).
influenza (2 papers, 2017 to 2024). An acute viral infection of the respiratory tract, occurring in isolated cases, in epidemics, or in pandemics; it is caused by serologically different strains of viruses (influenzaviruses) designated A, B, and C, has a 3-day incubation period, and usually lasts for 3 to 10 days. "Furthermore, to gain a deeper understanding, it’s vital to include other infection-control groups in comparisons, such as examining the incidence rates of MOG-ON and AQP4-ON during influenza seasons." (PMID 38988608, 2024).